TERT (telomerase reverse transcriptase)
Diseases named in the same sentence as TERT in open-access papers (continued):
Sharing a sentence is not in itself a finding about the gene and the disease.
cancer (continued). "The mechanism of reactivation of telomerase in cancers has been recently reported to take place by recruitment of transcription factor such as GABPA or BRAF specifically to mutant TERT promoters, hence driving TERT transcription." (PMID 29907642, 2018). "Reactivation of TERT leads to cancer progression by canonical (telomere dependent) and non-canonical mechanisms." (PMID 30093619, 2018). "The relative expression level of TERT and TREC transcripts was 8.2 ± 0.45 and 18.8 ± 4.79; 6.5 ± 0.56 and 17.3 ± 2.99; and 2.6 ± 0.29 and 11.8 ± 6.67% in the untreated A-549, MDA-MB-231 and U87-MG cancer cells, respectively." (PMID 30460075, 2017). "In human tissue samples, expression levels of TERT in the cancer tissues were significantly higher than those in matched normal mucosa (P = 0.0388)." (PMID 29137437, 2017). "We applied this methodology to our study of an intergenic GWAS susceptibility variant, and established a role for the regulatory element in driving TERT (but not CLPTM1L) gene expression across multiple cancer types." (PMID 28447668, 2017). "The factors that discriminate Myc-dependent TERT regulation during normal development from cancer are not known and need further investigation." (PMID 28184371, 2017). "We considered telomere length (TL), ratio of telomere length in cancer to non-cancer tissue (T/N ratio), telomerase activity and TERT levels; their relation with clinical variables and their role as prognostic markers." (PMID 26913901, 2016). "It is currently unclear whether MetIs can act as a prognostic factor independently of TERT or telomerase activity, which calls for further clinical investigations in additional cohorts of MTC or other cancer patients." (PMID 26870890, 2016). "In addition, we also found that the expression of TERT and CLPTM1L was higher in the NPC tissues compared to the non-cancer nasopharyngeal tissues." (PMID 26621837, 2016). "If many genes are like TERT, WGS might indeed pave the way for identifying a comprehensive catalogue of cancer genes." (PMID 27417679, 2016). "Unlike HepG2, this cell line was not derived from cancer cells, but rather from skeletal muscle of a 19 year-old healthy donor and a cell line developed by retroviral knock-in of the TERT and CDK4 genes." (PMID 26823999, 2016). "Neither TERT-CLPTMIL rs2853668 nor TERT rs2853676 significantly altered miRNA expression in normal colonic mucosa or miRNA expression between carcinoma and normal colorectal mucosa." (PMID 27627813, 2016). "One of the novel associations (rs13174814) maps to a second region in the TERT promoter and the other (rs62329728) is in the promoter region of CLPTM1L; neither are correlated with previously reported cancer-associated SNPs." (PMID 25487306, 2015). "Previous researches show that TERT is expressed at low levels or not detectable in normal somatic cells and tissues while its expression is up-regulated in most carcinoma cells and highly proliferative organs." (PMID 24376652, 2013). "TERT and TINF2 RNA levels did not associate with TCN, a finding also observed in other human cancer cell lines." (PMID 22952882, 2012). "TERT cells are useful cell culture controls for drug discovery as they retain relatively normal geno- and phenotypes and do not acquire cancer cell characteristics." (PMID 21219631, 2011). "Despite being associated with several cancers, the results of this large, multicohort investigation into a comprehensive range of aging phenotypes in a middle- to older-aged UK population do not support the hypothesis that SNP rs401681 in the TERT-CLPTM1L locus influences other aging traits." (PMID 21332924, 2011). "Notably, TERT plays a pivotal role as a transcription (co-)factor, regulating gene expression and modulating key signaling pathways, such as WNT/β-catenin, NF-κB p65, and MYC, which drive cancer onset and progression." (PMID 40227701, 2025).
cancer (continued). "First, we analysed two telomerase-positive tumors (HCT116 and SK-MEL28), normally expressing TERT and presenting telomerase activity; then, we induced TERT expression in two TERT-lacking cancer cell lines (U2OS and SAOS), characterized by the alternative mechanism of telomere lengthening (ALT)." (PMID 41144538, 2025). "Moreover, it would be of interest to test how TL-dependent TERT regulatory mechanisms affect senescing primary cells and telomerase-negative cancer cells (with ALT mechanism)." (PMID 41026782, 2025). "Moreover, our analysis of cancer cells reveals that Telo-seq can efficiently distinguish between TERT+ and ALT+ cancer cells, establishing Telo-seq as a reliable method of TMM prediction, an essential prerequisite to target TMM-specific vulnerabilities in a personalized cancer therapy." (PMID 38890299, 2024). "In a recent in vitro and animal study we demonstrated that BRAF/MEK inhibitors could induce strong therapeutic responses in cancer cells harboring both BRAF V600E and mutant TERT promoter through causing robust apoptosis but not cells harboring WT TERT." (PMID 38735658, 2024). "These metastases had no other evidence of a TLM (i.e., they did not overexpress TERT, and had neither detectable C-circles nor an increased telomere length ratio) and had no recurrent cancer gene alterations that may explain metastatic progression." (PMID 38978571, 2024). "The purpose of this study was to characterize the relative invasiveness of three available endometriotic cell lines (EEC12Z, iEc-ESCs, tHESCs) to cancer cell lines (MDA-MB-231, SW1353 and EM-E6/E7/TERT) and assess whether the relative invasiveness was consistent across different invasion assays." (PMID 37371583, 2023). "Based on the TERT minigene study in HeLa cells, TCGA data in LUAD patients, and iPSC data, we classified the SFs into either FL TERT-promoting (green color), minus beta TERT-promoting (red color), or non-effector (no color) to summarize their predicted behavior in iPSCs and cancer cells." (PMID 37531400, 2023). "EGF activates TERT transcription in cancer cells but not in somatic cells." (PMID 37233461, 2023). "However, TERT gene therapy in mice resets cell aging and increases longevity without increasing the frequency of cancers." (PMID 36552277, 2022). "ATRX KO induces ALT activation in the telomerase-negative cancer cells but, alone, is not sufficient to activate ALT in telomerase-positive cancer cells, in which it was necessary to also create gene KO of TERT through the CRISPR-Cas9 system to achieve comparable results." (PMID 36497228, 2022). "Cancer cells express telomerase but do not entirely escape telomere instability as they often possess short telomeres; hence there is often selection for genetic alterations in the TERT promoter that result in increased telomerase expression." (PMID 35920280, 2022). "Even though numerous genetic association studies investigate the association of variant in TERT and CLPTM1L regions and cancers or non-cancer disease susceptibility, the conclusions are not always consistent and the functional mechanisms remain unclear." (PMID 35847915, 2022). "Indeed, most of the first studies on the non-telomeric functions of TERT showed that its downregulation induces apoptosis in cancer cells." (PMID 36499514, 2022).
cancer (continued). "The aberrant TERT promoter hypermethylation has been observed in cancer tissues and cells, including TCs, and the hypermethylation in the upstream of the transcription start site (UTSS) identified as an epigenetic mechanism to induce TERT expression by erasing repressor binding." (PMID 36394204, 2022). "Aside from obvious cases involving oncogenes, such as TERT, disentangling gene amplifications that drive cancer evolution from those that arise as a result of passenger SCNA events remains a challenging task for cancer biologists, particularly since SCNAs can encompass many genes." (PMID 34573358, 2021). "Indeed, the correlation between TERT and MYC is well-documented in various cancers." (PMID 33599797, 2021). "However, the non-telomeric functions of telomerase still remain unaddressed and further experiments are necessary to understand how the non-canonical roles of TERT regulate gene expression and cancer progression." (PMID 33599797, 2021). "Despite T cell responses to “universal” TAAs can be detected also in patients with early stages of cancer, no significantly higher levels of T-cells specific for TERT and Survivin were detected at baseline or at the time of diagnosis of cancer in the blood of T and NT patients." (PMID 34746013, 2021). "At the same time, targeting its expression specifically in cancer, regardless of TERT status, could serve as an attractive anti-tumor strategy." (PMID 33599797, 2021). "Unlike TERT, mutations in the TERC gene, or its promoter, are less prevalent in cancer." (PMID 33599797, 2021). "After incorporating wild-type TERT and mutant TERT with stages I, II, and III/IV of the AJCC TNM system 8th edition (TNM-8), we generated six combinations and calculated 10-year and 15-year CSS and adjusted hazard ratios (HRs) for cancer-related death using Cox regression." (PMID 34208345, 2021). "However, the noncanonical roles of TERT in cancer and their relevance in its progression and response to therapy remain poorly understood." (PMID 33713376, 2021). "Thus, by targeting LRP/LR with siRNA technology, its consequent effects on TERT/telomerase and TRF-2 observed in this study may compromise several key hallmarks of cancer." (PMID 33836696, 2021). "Therefore, it is possible that TAF-I is involved in the transcriptional activation of TERT through the maintenance of low CpG methylation level around TSS but not THOR in a variety of cancer cells." (PMID 34489496, 2021). "Thus, while TERT appears to be non-essential, the maintenance of telomere length is likely to be required for cancer development." (PMID 34830134, 2021). "Nevertheless, the mechanism by which TERT and TUG1 maintain dual localization in the nucleus and cytoplasm remains unknown, but could potentially provide important insights into their biology and targeting in cancer." (PMID 34083519, 2021). "Thus, it is not surprising that TERT expression levels in tumors correlate with poor prognosis in several cancer types including lung and breast cancers." (PMID 32630460, 2020). "Indeed, evidence of TERT non-telomeric activities—regulation of apoptosis, DNA damage response, and transcription among others—in the context of cancer has amassed since the late 1990s." (PMID 32599885, 2020). "Hypomethylation of this TERT proximal promoter region may be a universal correlation and possibly a necessity for TERT expression in cancer cells, regardless of allelic expression status." (PMID 33245585, 2020). "This further suggests that TPMs may be advantageous for cancers initiating from tissues with low or undetectable TERT expression while providing no selective advantage to cancers arising from stem cell compartment." (PMID 32674474, 2020).
cancer (continued). "Therefore, TERT is regarded as a central regulator of the hallmarks of cancer, and therapeutics targeting both its canonical and noncanonical functions are suggested to be more effective in cancer treatment." (PMID 33239622, 2020). "In addition to the role of TERT in reestablishing telomerase activity that elongates telomeres, recent observations also reveal multiple oncogenic activities associated with telomerase subunit TERT in cancer which may or may not require catalytically active telomerase." (PMID 32674474, 2020). "The goal is to review the comprehensive spectrum of TERT pro-malignant activities, both telomeric and non-telomeric, which may explain the prevalence of its upregulation in cancer." (PMID 32599885, 2020). "Likewise, TERTp mutations are generally absent from cancers where telomere elongation is ensured by ALT or TERT copy-number duplications." (PMID 32204305, 2020). "However, the mechanism of TERT upregulation in cancers with low frequency of TPMs are not fully elucidated so far." (PMID 33061812, 2020). "While −124 mutants are known to have a mutation that recruits ETS transcription factors such as GABP to activate TERT expression, still approximately 78% of cancer cell lines have wild‐type TERT promoters and do not contain known activating cis‐acting genetic alterations." (PMID 33245585, 2020). "The dependence of TERT expression on all three signaling pathways with IL-2 and with IL-15 in CD8 T cells, suggests that any therapies that inhibit MEK/ERK pathways used in cancer patients are likely to affect proliferation of CD8 T cells to a greater extent than NK cells or NK-like cells." (PMID 33537030, 2020). "Specifically, human TERT promoter drives GAL4 expression in a cancer-specific manner, and GAL4 subsequently binds to UAS to activate a promoter driving Cas9 nuclease expression, ultimately promoting preferential Cas9 expression in cancer cells through a genetic cascade." (PMID 31035374, 2019). "Interestingly, the pathological analysis of all mice postmortem revealed that ectopic TERT expression by AAV9 did not increase cancer incidence compared to treatment with the GFP-expressing AAV9 control vector." (PMID 31035374, 2019). "Therefore, endowed with these non-telomeric functions, TERT can participate to all the major characteristics of the cancer phenotype described by Hanahan and Weinberg (2000, 2011)." (PMID 31911897, 2019). "A recent systemic analysis of 18,430 samples across 31 cancer types has discovered that approximately 22% of tumors without detectable TERT expression might be absent from the two mechanisms of telomere maintenance." (PMID 31179925, 2019). "Indeed, TERT synergized with Sp1 to stimulate the DNMT3B promoter activity, and moreover, Sp1 inhibition significantly attenuated TERT-mediated DNMT3B up-regulation, while its over-expression restored DNMT3B expression in TERT-depleted cancer cells." (PMID 31284662, 2019). "Interestingly, the antisense oligonucleotide treatment did not affect telomere length; thus, the reduction in the viability of TERT-positive cancer cells was not due to telomere attrition." (PMID 31035374, 2019). "In BRG1-deleted cancer cells, BRM, p54(nrb), PSF, and phosphorylated RNA polymerase II are specifically co-localized in a region incorporating an alternative splicing acceptor site of TERT exon 7, which contributes to the generation of full-length TERT transcripts." (PMID 31284662, 2019). "SFN may exhibit Nrf2-independent anti-cancer activities by enhancing the transcription of tumor suppressor genes, possibly by influencing DNA methylation, activation of caspase-3, induction of cell cycle arrest, and inhibition of ERα, DNMT and TERT." (PMID 29518137, 2018). "Thus, and in contrast to the mono system, the normal balance of TERT in these cells is not affected and an elevation of the transcription inhibition factors is less expected, both in healthy as well as in cancer cells." (PMID 29938000, 2018).
cancer (continued). "In the majority of cancer cells and in continuously dividing germ line cells, however, telomere erosion is mitigated by the action of telomerase – a specialized ribonucleoprotein (RNP) complex minimally composed of telomerase RNA (TR) and the telomerase reverse transcriptase (TERT) enzyme." (PMID 30355447, 2018). "Studies after ectopic expression of TERT showed enhanced translation in cells to regulate cancer cell proliferation independent of telomere length, suggesting that the effects of TERT could be telomere-independent." (PMID 28218725, 2017). "TERT, the catalytic subunit of telomerase, is the most important target among other telomerase subunits, because it has a major role in the reconstitution of telomerase activity as well as having various non-telomeric functions in cancer progression." (PMID 28264499, 2017). "Therefore, we hypothesize that the elevated cytoplasmic TERT in CCHCC is responding to abnormal glucose or lipid metabolism, thereby inhibiting cell apoptosis and promoting cancer cell survival." (PMID 28460432, 2017). "More than 90 % of cancers acquire the capability to replicate indefinitely through telomerase expression, a ribonucleoprotein complex containing an internal RNA component (TR or TERC) and a catalytic protein, TERT, with telomere-specific reverse transcriptase activity." (PMID 27501725, 2016). "However, the DR mimetic rapamycin has been reported to decrease telomerase activity and TERT protein levels in cancer cells in the absence of transcriptional changes in TERT expression." (PMID 27777385, 2016). "Given the ample spectrum of critical functions modulated by TERT, its inhibition could represent a promising strategy to improve cancer treatment, regardless of telomere length." (PMID 28032863, 2016). "Genetic variation near TERT and TERC may influence cancer risk independent of its effect on telomere length, as telomerase has been shown to upregulate glycolysis and may contribute to the Warburg effect." (PMID 26646793, 2015). "However, the FDA has not yet approved anti-cancer drugs targeting the TERT gene." (PMID 39669196, 2024). "Additionally, it has been observed that TERT’s effects might have functions independent of its role in telomeres and could contribute to the proliferation of cancer cells through other mechanisms." (PMID 39188883, 2024). "Lee and colleagues also identified a region upstream of the TERT core promoter which was hypermethylated in cancer lines but unmethylated in normal lines lacking TERT expression, hypothesized to inhibit the binding of repressive proteins and allow for TERT transcription." (PMID 39095874, 2024). "Given the nonconventional DNA methylation pattern at the TERT locus with hypermethylation around the TPM sites in cancer cells and hypomethylation in noncancerous primary cells, we next tested whether the DNA methylation pattern is altered between cell lines with different TPM status." (PMID 37918959, 2023). "Thirdly, clinical markers that may affect bone metastasis of cancer, including BRAF mutation, calcitonin, TERT mutation, and Ki-67 index, were not included in this study, and we will continue to expand our data collection to further improve our model in the future." (PMID 36950687, 2023). "Indeed, we also found in these cancers a significant co-occurrence of FGFR3 SVs with CDKN2A/B and TERT, as has been found previously, suggesting that it may be possible to stratify patients according to these alterations, but clinical data are required to confirm this hypothesis." (PMID 36462464, 2022).